MT-CYB (mitochondrially encoded cytochrome b)
Description:
Component of the ubiquinol-cytochrome c reductase complex (complex III or cytochrome b-c1 complex) that is part of the mitochondrial respiratory chain. The b-c1 complex mediates electron transfer from ubiquinol to cytochrome c. Contributes to the generation of a proton gradient across the mitochondrial membrane that is then used for ATP synthesis.
Synonyms: COB; CYTB; UQCR3; formerly MTCYB
Tractability: Small molecule: a structure with a bound ligand is known. Antibody: UniProt predicts a signal peptide or a membrane-spanning region.
Gene: Protein-coding gene on chromosome MT (14,747 to 15,887, forward strand). Ensembl gene ENSG00000198727.
Subcellular location: Mitochondrion inner membrane
Subcellular location (Human Protein Atlas): Mitochondria
Pathways (Reactome):
Metabolism: Complex III assembly; Respiratory electron transport
Metabolism of proteins: Mitochondrial translation termination
Gene Ontology:
Molecular function: quinol-cytochrome-c reductase activity; electron transfer activity; oxidoreductase activity
Biological process: cellular respiration; mitochondrial electron transport, ubiquinol to cytochrome c; proton transmembrane transport; respiratory electron transport chain
Cellular component: mitochondrial inner membrane; mitochondrion; respiratory chain complex III; membrane
Gene-disease validity (ClinGen):
ClinGen rates the evidence that MT-CYB causes each of these diseases.
mitochondrial disease (mitochondrial): Definitive.
Homologues: Orthologues: chimpanzee MT-CYB (93% identical), macaque CYTB (81% identical), rabbit MT-CYB (81% identical), guinea pig MT-CYB (78% identical), mouse mt-Cytb (78% identical), pig CYTB (78% identical), rat Mt-cyb (78% identical), tropical clawed frog CYTB (73% identical), zebrafish mt-cyb (70% identical), Drosophila melanogaster mt:Cyt-b (61% identical), Caenorhabditis elegans WBGene00000829 (42% identical).
Diseases named in the same sentence as MT-CYB in open-access papers:
MT-CYB is named in the same sentence as 115 diseases in open-access papers, as found by Europe PMC text mining. Sharing a sentence is not in itself a finding about the gene and the disease. The quoted sentences say what the papers report.
bladder cancer (8 papers, 2015 to 2025). "This activated mutant of MT-CYB, specifically associated with bladder cancer, also functionally increased anchorage-independent growth and mitochondrial biogenesis, as well as mt-DNA content." (PMID 27136895, 2016). "MT-CYB mutations have also been detected in human bladder carcinomas." (PMID 27136895, 2016). "Another study reported that a mitochondrially encoded cytochrome B (CYTB) gene mutation (a 21-bp deletion) promoted the growth and bioenergetic capacity of bladder cancer-derived cells." (PMID 41154474, 2025).
Parkinson disease (8 papers, 2013 to 2026). A progressive degenerative disorder of the central nervous system characterized by loss of dopamine producing neurons in the substantia nigra and the presence of Lewy bodies in the substantia nigra and locus coeruleus. "Similarly, decreased expression of mitochondrial genes such as MT‐CO1, MT‐CYB, and MT‐ATP6 in dopaminergic subclusters points to impaired oxidative phosphorylation, which could contribute to parkinsonism, ataxia, and other movement disorders arising from energy failure in motor circuitry." (PMID 41355579, 2026).
COVID-19 (7 papers, 2021 to 2025). A disease caused by infection with severe acute respiratory syndrome coronavirus 2. "In conclusion, one novel mtDNA mutation was identified in this study, and some of the mutations identified in the MT-CYB as well as MT-ATP6 genes, including the novel mutation, are relatively common in the COVID-19 patient group." (PMID 40839580, 2025). "This study aims to investigate mutations in the MT-CYB and MT-ATP6 genes of mtDNA in COVID-19 patients and their association with disease outcomes." (PMID 40839580, 2025). "By comparing the upregulated genes between COVID-19 patients and recovered individuals, we found that 21 genes (i.e., RPL4, MT-ND2, SCD5, MT-CYB, EZR) were shared between the conditions." (PMID 36059456, 2022).
breast carcinoma (6 papers, 2016 to 2023). "Among the already known variants is the rs2853508 mutation in the MT-CYB gene, which may have a pathogenic effect in breast cancer according to dbSNP." (PMID 31267007, 2019). "Interestingly, the rs2853508 variant in the cytochrome b gene (MT-CYB) has previously been shown to likely be pathogenic in breast cancer." (PMID 31267007, 2019). "Interestingly, they observed that two mitochondrial genes, namely MT-ATP6 (complex V) and MT-CYB (complex III) showed the highest number of variants in the high-risk breast cancer patients." (PMID 27136895, 2016).
Leber hereditary optic neuropathy (5 papers, 2010 to 2016). Leber's hereditary optic neuropathy (LHON) is a mitochondrial neurodegenerative disease affecting the optic nerve and often characterized by sudden vision loss in young adult carriers. "Mutations in MTCYB, encoding cyt b, have been found linked to a wide range of neuromuscular disorders, but also to Leber hereditary optic neuropathy and to multisystem disorders." (PMID 25452764, 2014). "Mutations in MT-CYB have also been associated with Leber hereditary optic neuropathy (LHON) [MIM: 535000], a maternally inherited disease resulting in acute or subacute loss of central vision due to optic nerve degeneration." (PMID 20862300, 2010).
ovarian carcinoma (5 papers, 2010 to 2025). A malignant neoplasm originating from the surface ovarian epithelium. "MT-CYB mutations have been implicated in ovarian carcinoma previously." (PMID 39941116, 2025). "Through further analysis of these key genes and cancer stem cell subpopulation, more critical genes can be obtained as LCP2, FCGR3A, COL1A1, COL1A2, MT-CYB, CCT5, and PAPPA, are closely associated with ovarian cancer." (PMID 35360863, 2022). "Through the analysis of stemness-related key genes and tumor stem cell subpopulations, LCP2, FCGR3A, COL1A1, COL1A2, MT-CYB, CCT5, and PAPPA are closely related to ovarian cancer." (PMID 35360863, 2022). "In our new analytical process, the key genes related to ovarian cancer are identified as LCP2, FCGR3A, COL1A1, COL1A2, MT-CYB, CCT5, and PAPPA, which may have important significance in ovarian cancaer and drug therapy." (PMID 35360863, 2022). "Therefore, COL1A1, COL1A2, MT-CYB, CCT5, and PAPPA may be potential genetic biomarkers for the treatment of ovarian cancer." (PMID 35360863, 2022).
epilepsy (4 papers, 2012 to 2025). A brain disorder characterized by episodes of abnormally increased neuronal discharge resulting in transient episodes of sensory or motor neurological dysfunction, or psychic dysfunction. "Other mitochondrial proteins with epilepsy backgrounds that were observed more often in the IE group included MT-CYB and MT-ND5." (PMID 32823271, 2020).
hepatocellular carcinoma (4 papers, 2021 to 2025). A malignant tumor that arises from hepatocytes. "A recent report showed miR-181a-5p potentially targeting the MT-CO2 and cytochrome b (MT-CYB) genes in human hepatocellular carcinoma." (PMID 35887244, 2022).
Leigh syndrome (4 papers, 2022 to 2025). A progressive neurological disease defined by specific neuropathological features associating brainstem and basal ganglia lesions. "Here, we report for the second time the occurrence of the m.15635T>C (p.Ser297Pro) variant affecting the MT-CYB gene in a patient with Leigh syndrome, previously found in a very severe sporadic case of fatal neonatal polyvisceral failure." (PMID 39940884, 2025). "Variants in this gene primarily are associated with Leigh syndrome and exercise intolerance; however, an infantile form of MELAS has also been caused by a 4-bp deletion affecting MT-CYB." (PMID 35699875, 2022).
Obesity (4 papers, 2014 to 2024). Accumulation of substantial excess body fat. "For example, we recently reported that mice harbouring another maternally inherited natural mtDNA variant, m.15124A>G in the mitochondrially encoded cytochrome b gene (mt-Cytb) in complex III, developed spontaneous middle-aged obesity only in males." (PMID 31337008, 2019). "One of such examples is the polymorphism in the mitochondrially encoded cytochrome b gene (MT-CYB), which has been reported to be associated with middle-aged obesity in the Japanese population though the functional consequence of the variation in the MT-CYB gene that is yet to be elucidated." (PMID 31085998, 2019).
brain tumor (3 papers, 2021 to 2022). "In conclusion, due to the importance of cytochrome b in the respiratory chain, mutations in MT-CYB may contribute to brain tumour formation." (PMID 36292984, 2022). "Three MT-CYB polymorphisms: A14793G, A15758G and A15218G, as well as the MT-CO1 G7444A, MT-CYB T15663C and G8959A (ATP6) mutations, may affect the function of mitochondria, thus potentially playing an important role in the formation of brain tumours." (PMID 36292984, 2022).
leprosy (3 papers, 2013 to 2024). Leprosy is a chronic infectious disease affecting primarily the skin and peripheral nervous system. "The MT-CYB gene codifies a subunit of cytochrome b oxidase (Complex III), involved in oxidative phosphorylation, and it has been described as less expressed in leprosy patients when compared to non-leprosy population." (PMID 38062538, 2023). "Other mRNAs were also less expressed in leprosy patients when compared to non-leprous samples, such as Bad, IL10, IL12 as well as several mitochondrial genes (mtCOX2, mtND1, mtND3 mtND5 mtATP6, and mtCYB)." (PMID 23798993, 2013).
mitochondrial myopathies (3 papers, 2013 to 2022). "Mutations in the mitochondrially encoded structural subunit of Complex III, the cytochrome b gene (MT-CYB), have been largely associated with isolated mitochondrial myopathy and exercise intolerance." (PMID 31435670, 2019).
colon cancer (2 papers, 2016 to 2018). "Genetic evidence of a role for MT-CYB in cancer comes from studies on breast and colon cancers." (PMID 27136895, 2016).
depression (2 papers, 2018 to 2023). "For example, MT-CYB, which was found to interact with CRP for self-reported depression, is the only mitochondrial DNA encoded subunit of respiratory complex III." (PMID 37344456, 2023).
histiocytoid cardiomyopathies (2 papers, 2016 to 2019). "Patients carrying different mutations in the MTCYB gene, encoding for cytochrome b, showed HCM or histiocytoid cardiomyopathy." (PMID 31842377, 2019). "Hypertrophic, dilated, and histiocytoid cardiomyopathies were reported in individuals with complex III deficiency and mutations in the MTCYB gene encoding cytochrome b." (PMID 27504452, 2016).
lactic acidosis (2 papers, 2010 to 2021). Metabolic acidosis characterized by the accumulation of lactate in the body. "We have analyzed the pathogenic role of a novel homoplasmic mutation (m.15533 A>G) in the cytochrome b (MT-CYB) gene in a patient presenting with lactic acidosis, seizures, mild mental delay, and behaviour abnormalities." (PMID 20862300, 2010). "Cytochrome b (cyt b) is the only mtDNA-encoded subunit of Complex III; mutations in its gene, mitochondrially encoded cytochrome b (MT-CYB), are characterized by skeletal muscle involvement, exercise intolerance, and lactic acidosis." (PMID 34827632, 2021).
colorectal cancer (1 paper, 2025). A primary or metastatic malignant neoplasm that affects the colon or rectum. "Further supporting the role of mitochondrial genes in cancer progression, several studies reported a significant increase in the expression of multiple mitochondrial genes—including MT-COI, MT-CYB, MT-ND1, and MT-RNR1—in colorectal cancer tissues compared with adjacent normal tissue." (PMID 40974979, 2025).
dilated cardiomyopathies (1 paper, 2024). "Alterations in mtDNA genes such as NADH-dehydrogenase genes (MT-ND1, MT-ND5 and MT-ND6), cytochrome b (MT-CYB), cytochrome c oxidase I and II (MT-CO1 and MT-CO2), and ATP synthase 6 (MT-ATP6), have been described in dilated cardiomyopathies." (PMID 38391966, 2024).
hypertrophic cardiomyopathy (1 paper, 2013). A condition in which the myocardium is hypertrophied without an obvious cause. "Mutations in mitochondrial DNA, particularly in MT-CYB coding for cytochrome B in complex III (CIII), have been associated with isolated hypertrophic cardiomyopathy (HCM)." (PMID 24498601, 2013).
Infertility (1 paper, 2022). "The current findings showed an association between the occurrence of mutations in the MT-CYB gene and men’s infertility." (PMID 35118571, 2022). "The current study showed a significant correlation between certain MT-CYB gene SNPs (rs527236194 (P = 0.0005), rs28357373 (P = 0.0439), and rs41504845 (P = 0.0038)) and the incidence of men’s infertility." (PMID 35118571, 2022). "In addition, more studies on the MT-CYB gene are required on different populations to reveal the exact role of the reported SNPs on men’s infertility." (PMID 35118571, 2022).
male infertility (1 paper, 2022). The inability of the male to effect fertilization of an ovum after a specified period of unprotected intercourse. "In other studies, genetic alterations in the MT-CYB gene were proposed to be associated with the development of male infertility." (PMID 35118571, 2022). "Thus, in the current study, we aimed to investigate the effect of mutations in the MT-CYB gene on sperm motility and male infertility." (PMID 35118571, 2022).
mild cognitive impairment (1 paper, 2023). "The mitochondrial coding and non-coding RNA are increased in the circulating extracellular vesicles in AD and mild cognitive impairment (MCI); the AD genes in the category of this study include MT-ND1-4,6, MT-ND4L, MT-ATP6, MT-ATP8, MT-CYB (or MT-CYBT), MT-CO1, and MT-RNR1." (PMID 36982253, 2023).
Pruritus (1 paper, 2024). Pruritus is an itch or a sensation that makes a person want to scratch. "Mitochondrially encoded cytochrome B (cytochrome b, MT-CYB or CYTB), a member of the oxidative phosphorylation system, can affect the production of free radicals, which is also upregulated in all pruritus groups." (PMID 38577622, 2024).
retinitis pigmentosa (1 paper, 2021). Retinitis pigmentosa (RP) is an inherited retinal dystrophy leading to progressive loss of the photoreceptors and retinal pigment epithelium and resulting in blindness usually after several decades. "So far, mutations in MT-CYB have been associated with LHON, retinitis pigmentosa and cataract." (PMID 34976016, 2021).
tumor (20 papers, 2014 to 2026). "However, five genes (MT-CO1, MT-CYB, MT-DLOOP1, MT-ND1 and MT-ND5) not only presented germline variants, but also different somatic variants exclusive to tumor and internal control groups, indicating a possible association of such genes and variants with tumor development." (PMID 31673122, 2019). "Taken together with our current data, these results suggest that atovaquone treatment may be an effective new strategy for targeting the Cytochrome bc1 complex (especially MT-CYB and CYC1) in cancer, to prevent the proliferative expansion of CSCs and tumor growth." (PMID 27136895, 2016).
cancer (18 papers, 2008 to 2025). A tumor composed of atypical neoplastic, often pleomorphic cells that invade other tissues. "It seems that mutations in the MT-CYB gene are involved in remodeling mitochondrial metabolism with increases in the production of reactive oxygen species (ROS) within cancer cells." (PMID 39941116, 2025). "RNA sequencing revealed the downregulation of five genes, three of which were mitochondrial genes—MT-CYB, MT-ND1, and MTND2P28—implicated in cancer progression." (PMID 40974979, 2025). "The loci p.L105P and p.A459T in ND5 (COSM9490819/ COSM1132235) and p.A59T in MT-CYB (COSM1138286) were detected in other cancers in the COSMIC database." (PMID 37038181, 2023). "This highly variable nature of the MT-CYB gene is also the reason for the development of cancers." (PMID 37397663, 2023). "However, very little is known about the role of MT-CYB and the Cytochrome bc1 complex in cancer." (PMID 27136895, 2016). "Among them, COL1A1, COL1A2, MT-CYB, CCT5, and PAPPA have been reported to be closely related to cancer." (PMID 35360863, 2022). "In addition, six transcripts (MT-ATP6, MT-CO1, MT-CYB, MT-ND1, MT-ND6, and MT-RNR1) were quantified in 62 cancer tissues by real-time RT-PCR." (PMID 18842121, 2008). "Also among the upregulated genes were mitochondrial protein coding genes (MT-ND3, MT-ND4L, MT-ND4, MT-ND2, MT-CYB, MT-ND1, MT-CO1 etc), which may be as a result of the elevated metabolism characteristic of cancer cells to sustain their survival." (PMID 29132323, 2017).
neurodegenerative disease (2 papers, 2021). A disorder of the central nervous system characterized by gradual and progressive loss of neural tissue and neurologic function. "Here, we found that the species of Mn can increase or arrest the expression of genes such as MT-CO1, MT-CYB, MT-ND4, and COX4I2, which are associated with glycolysis and glycogenesis, and oxidative phosphorylation, along with neurodegenerative diseases such as AD, HD, and PD." (PMID 34941782, 2021).
MT-CYB also shares sentences with these, for which no sentence is quoted: malaria (35 papers); infection (33); Chagas disease (8); asthenozoospermia (4); leishmaniasis (4); parasitemia (4); cutaneous leishmaniasis (3); cyst (3); diabetes (3); glioblastoma (3); Parkinsonism (3); Alzheimer disease (2); Ataxia (2); Babesia infection (2); co-infection (2); diabetic retinopathy (2); epithelioma (2); Huntington disease (2); Hypertension (2); lung injury (2); lymphoma (2); MELAS (2); mitochondrial disease (2); myopathy (2); Sepsis (2); trypanosomiasis (2); tuberculosis (2); Anxiety (1); asthma (1); atherosclerosis (1).
A further 57 diseases each share a sentence with MT-CYB in 1 paper.